RPL23AP42 (ribosomal protein L23a pseudogene 42)
Synonyms: RPL23A_13_431
Gene: Processed pseudogene on chromosome 3 (161,429,127 to 161,429,597, reverse strand). Ensembl gene ENSG00000234851.
Diseases named in the same sentence as RPL23AP42 in open-access papers:
RPL23AP42 is named in the same sentence as 1 disease in open-access papers, as found by Europe PMC text mining. Sharing a sentence is not in itself a finding about the gene and the disease. The quoted sentences say what the papers report.
tumor (1 paper, 2025). "For example, elevated expressions of CMTR1, TSPYL1, or RPL23AP42 are associated with poorer survival, aligning with their hypothesized roles in promoting tumor progression or interfering with gene regulation." (PMID 40725410, 2025).